PTBP3 (polypyrimidine tract binding protein 3)
Diseases named in the same sentence as PTBP3 in open-access papers (continued):
Sharing a sentence is not in itself a finding about the gene and the disease.
gastric cancer (continued). "Thus, a question remains whether the function of PTBP3 in gastric carcinoma tumour formation and metastasis is related to PTBP3-regulated alternative splicing of CAV1." (PMID 29752441, 2018). "The splicing factor PTBP3 promotes COX11 exon skipping, allowing gastric cancer organoids to evade cuproptosis." (PMID 40270362, 2025). "PTBP3-mediated exon 4 skipping in COX11 pre-mRNA is critical for tumor cell survival and progression in gastric cancer peritoneal metastasis, providing a potential therapeutic strategy targeting copper metabolism." (PMID 41158129, 2025). "Therefore, it is essential to investigate whether transcription factors are involved in the alternative splicing of PTBP3 and to identify the genes regulating PTBP3 expression, which may contribute to its elevated levels in gastric cancer peritoneal metastatic tissues." (PMID 40270362, 2025). "Using gastric cancer cells and patient‐derived organoids (PDO), the role of PTBP3 in promoting tumor invasion and proliferation is investigated." (PMID 40270362, 2025). "To confirm whether COX11 undergoes exon skipping mediated by PTBP3, we first conducted agarose gel electrophoresis (AGE), which revealed two distinct transcripts—long and short forms—of the COX11 gene across various gastric cancer cell lines." (PMID 40270362, 2025). "Antisense oligonucleotide drugs targeting PTBP3‐mediated COX11 alternative splicing, in combination with copper ionophores, promote cuproptosis in organoids, thereby providing a therapeutic approach for gastric cancer peritoneal metastasis." (PMID 40270362, 2025). "However, in gastric cancer, PTBP3 promotes metastasis of gastric cancer by regulating CAV1 and reduces the sensitivity of gastric cancer cells to 5-Fu by the HDAC6/Akt/TYMS pathway." (PMID 32477006, 2020). "Although Hes1 inhibited the activity of the PTBP3 promoter, it failed to impact the protein expression of PTBP3, showing the complexity of gene expression regulation in gastric cancer cells." (PMID 32974175, 2020). "To evaluate the clinical significance of PTBP3 in gastric cancer, we conducted immunohistochemical analysis using a tissue microarray comprising 102 pairs of matched gastric cancer normal tissues and primary tumors, alongside 20 cases of non‐paired gastric cancer peritoneal metastatic tissues." (PMID 40270362, 2025). "To gain deeper insight into the molecular mechanisms by which PTBP3 orchestrates peritoneal metastasis in gastric cancer, we performed full‐length transcriptome sequencing on MKN45 cells with or without PTBP3 overexpression." (PMID 40270362, 2025). "Overall, PTBP3 mediates CAV1 signalling through alternative splicing, and CAV1α has a negative effect on the metastasis potential of gastric cancer cells following integrin/Src/FAK pathway activation." (PMID 29752441, 2018).
colorectal cancer (8 papers, 2019 to 2024). A primary or metastatic malignant neoplasm that affects the colon or rectum. "PTBP3 knockdown in colorectal cancer cell lines restricted CRC proliferative capacities in vitro and in vivo." (PMID 35136024, 2022). "Ptbp3 can promote the growth and metastasis of colorectal cancer through the activation of HIF-1α, and HIF-1α is involved in the ICH process." (PMID 32602850, 2020). "PTBP1 was frequently altered in colorectal cancer, pancreatic cancer, and ovarian cancer; PTBP2 was frequently altered in non-small cell lung cancer, lung cancer, and ovarian cancer; and PTBP3 was frequently altered in pancreatic cancer, soft tissue sarcoma, and colorectal cancer." (PMID 36203873, 2022). "However, the role of PTBP3 in colorectal cancer (CRC) remains poorly explored." (PMID 35136024, 2022).
hepatocellular carcinoma (8 papers, 2019 to 2024). A malignant tumor that arises from hepatocytes. "Recently, some researchers have showed that PTBP3 was overexpressed and functioned as an oncogene in breast, gastric and hepatocellular cancer." (PMID 35016691, 2022). "PTBP3 was highly expressed in most tumours, such as breast invasive carcinoma, colon adenocarcinoma and hepatocellular carcinoma." (PMID 35359851, 2022). "Recently, we and others have showed that PTBP3 was overexpressed and functioned as an oncogene in breast, gastric and hepatocellular cancers." (PMID 31291975, 2019). "PTBP3 was overexpressed in breast, gastric and hepatocellular cancers, suggesting PTBP3 might widely express in different kinds of cancers and be a potential biomarker for tumors." (PMID 31291975, 2019). "Most importantly, PTBP3 depletion abrogated UDP‐GlcUA‐increased TGFβR1 expression and its mRNA stability in hepatoma cells, indicating that PTBP3 is essential for UDP‐GlcUA‐induced TGFβR1 expression." (PMID 35979621, 2022). "To determine if PTBP3 is a direct target of UDP‐GlcUA, we conducted DARTS and CETSA assays in hepatoma cells." (PMID 35979621, 2022). "Although the role of PTBP3 in various human tumours was explored, the molecular function and mechanism of PTBP3 in hepatocellular carcinoma are still lacking." (PMID 37633911, 2023).
glioblastoma (6 papers, 2020 to 2025). The most malignant astrocytic tumor (WHO grade IV). "BTEB3 (also known as PTBP3) also showed strong enrichment and has been reported to promote glioblastoma tumorigenesis." (PMID 41007824, 2025). "MiR-210 promotes proliferation and inhibits apoptosis of glioblastoma multiforme cells by decreasing the expression of PTBP3." (PMID 32477006, 2020). "Interestingly, however, PTBP3 expressed in glioblastoma multiforme less than normal brain tissue." (PMID 32477006, 2020).
pancreatic cancer (5 papers, 2019 to 2022). "Furthermore, overexpression of the PTBP3 protein in lung and pancreatic cancers was associated with unfavorable prognosis." (PMID 30634466, 2019). "In the present study, we also found that down‐regulating ATG12 by reducing the expression of PTBP3 inhibited autophagy and increased sensitivity to gemcitabine in pancreatic cancer cells." (PMID 31989778, 2020). "Overall, these results indicate that PTBP3 is induced in human pancreatic cancer cells under hypoxia and is involved in hypoxia‐induced resistance to gemcitabine." (PMID 31989778, 2020). "The effects of hypoxia on gemcitabine resistance in pancreatic cancer cells underexpressing or overexpressing PTBP3 were then analysed." (PMID 31989778, 2020). "PTBP3 expression was higher in human pancreatic cancer than in paired adjacent tissues." (PMID 31989778, 2020). "To determine whether PTBP3 influences the malignancy of pancreatic cancer cells, we assessed whether the level of PTBP3 expression could alter proliferation by blocking the expression of PTBP3 in PANC‐1 cells and overexpressing PTBP3 in BxPC‐3 cells." (PMID 31989778, 2020). "Hypoxia significantly increased the expression of PTBP3 in pancreatic cancer cells in vitro." (PMID 31989778, 2020). "We have investigated the role of PTBP3 in tumour development and chemotherapeutic resistance in human PDAC tissues and pancreatic cancer cells." (PMID 31989778, 2020).
lung adenocarcinoma (4 papers, 2020 to 2023). A carcinoma that arises from the lung and is characterized by the presence of malignant glandular epithelial cells. "Existing studies show that PTBP3 overexpression induced epithelial-mesenchymal transition (EMT) and promotes the invasive growth and metastasis of breast tumor cells and lung adenocarcinoma cells." (PMID 37633911, 2023).
lung carcinoma (4 papers, 2017 to 2024). "For example, PTBP3 regulates lung cancer cell proliferation through the cell cycle and may be a potential target for lung cancer molecular therapy." (PMID 35359851, 2022). "Moreover, five of the remaining genes showed significant results in at least one of the lung cancer types, including LRRC27 and PLEKHB1 in LUAD and ARNTL2, FOSL1, and PTBP3 in LUSC." (PMID 39410631, 2024).
lymph node metastasis (4 papers, 2018 to 2022). "The univariate analysis showed that tumor size and PTBP3 expression were associated with lymph node metastasis." (PMID 32477006, 2020). "Moreover, PTBP3 expression is associated with differentiation, lymph node metastasis, and distant metastasis." (PMID 35359851, 2022). "Our previous study also found that PTBP3 expression is associated with lymph node metastasis." (PMID 29752441, 2018). "So we further analyzed whether PTBP3 can be used as a risk factor for lymph node metastasis." (PMID 32477006, 2020). "The positive correlation of the PTBP3 expression is present with three factors: First is with tumor differentiation (P = 0.003), second with lymph node metastasis (P = 0.004), and third with distant metastasis status (P = 0.002)." (PMID 32477006, 2020). "IHC analysis and real-time PCR data showed that PTBP3 was upregulated in the tissues of patients with lymph node metastasis." (PMID 29752441, 2018).
lung squamous cell carcinoma (3 papers, 2022 to 2023). "PTBP3 was highly expressed in most tumours and the overexpression of PTBP3 generally predicts poor overall survival and disease-free survival in patients of with adrenocortical carcinoma, lung squamous cell carcinoma, and pancreatic adenocarcinoma." (PMID 37633911, 2023). "The roles of Polypyrimidine tract-binding protein 3 (PTBP3) in regulating lung squamous cell carcinoma (LUSC) cells progression is unclear." (PMID 35016691, 2022). "PTBP3 overexpression generally predicts poor overall survival and disease-free survival in patients with adrenocortical carcinoma, lung squamous cell carcinoma, and pancreatic adenocarcinoma." (PMID 35359851, 2022).
non-small cell lung carcinoma (3 papers, 2020 to 2022). A group of at least three distinct histological types of lung cancer, including non-small cell squamous cell carcinoma, adenocarcinoma, and large cell carcinoma. "However, the correlation between PTBP3 expression and pathogenesis of non-small cell lung cancer (NSCLC) remains little known." (PMID 32477006, 2020). "A recent study suggested that PTBP3 promotes migration of non-small cell lung cancer (NSCLC) cells by regulating E-cadherin in the epithelial–mesenchymal transition signalling pathway and that there was a significant association between high PTBP3 expression in NSCLC tissues with poor OS." (PMID 35359851, 2022).
pancreatic adenocarcinoma (3 papers, 2020 to 2023). "In addition, we analysed the correlation between PTBP3, ATG12 and LC3 expression by using GEPIA, and the results indicated that PTBP3 had a strong correlation with the expression of ATG12 and LC3 in pancreatic adenocarcinoma." (PMID 31989778, 2020).
prostate carcinoma (3 papers, 2006 to 2022). A carcinoma that arises from epithelial cells of the prostate gland. "In prostate cancer cell lines and tissues, two enhancers located 63 kb upstream and 48 kb downstream of the PTBP3 region were identified to specifically loop to the PTBP3 promoter." (PMID 35757006, 2022). "The model of three dimensional chromatin conformation in the PTBP3 locus obtained for prostate cancer cell lines with high PTBP3 expression suggests, that the variable chromatin conformation is a mechanism that regulates its expression." (PMID 30634466, 2019). "The long-range chromatin looping interactions obtained in our study correlated with the overexpression of the PTBP3 gene in prostate cancer cell lines." (PMID 30634466, 2019). "Our study revealed two elements (−63 kb and +48 kb) in a 200-kb region across the locus that looped specifically to the PTBP3 promoter exclusively in PTBP3-expressing prostate cancer cell lines." (PMID 30634466, 2019). "This proposed looping model is clearly correlated with the expression of PTBP3 and suggests that chromatin conformation changes are the main epigenetic mechanism that regulates PTBP3 expression in prostate cancer cells." (PMID 30634466, 2019). "RNA sequencing expression data from the GEPIA analysis of the PTBP3 expression across normal and cancerous prostate tissue also demonstrate upregulation of the PTBP3 gene in prostate cancer tissue compared to normal samples." (PMID 30634466, 2019). "The most significant increase in the PTBP3 mRNA level was observed in the prostate cancer cell lines: PC3M cells (+/− 4.5-fold, p < 0.001) and the PC3 cells (+/− 2-fold, p < 0.01) compared to skin fibroblasts." (PMID 30634466, 2019). "Our consistent qPCR and ddPCR results indicate a significantly increased level of PTBP3 mRNA in prostate cancer cell lines compared to skin fibroblasts." (PMID 30634466, 2019). "Our results are consistent with the present of three-dimensional structural model and open chromatin form of the PTBP3 gene in prostate cancer cell lines." (PMID 30634466, 2019). "PTBP3 expression in prostate cancer cell lines is found significantly higher compared to skin fibroblasts using real-time PCR (p < 0.05) and digital droplet PCR (p < 0.01)." (PMID 30634466, 2019). "Our results reveal for the first time that long-range chromatin interactions between the −63 kb and +48 kb loci and the PTBP3 promoter regulate the expression of this gene in prostate cancer cells." (PMID 30634466, 2019). "PTBP3 was increased in prostate cancer cell lines compared to skin fibroblasts with GAPDH as the reference gene." (PMID 30634466, 2019). "Moreover, upregulation of the PTBP3 gene has been demonstrated in prostate cancer progression states versus benign prostate cancer samples (GDS1439/224618)." (PMID 30634466, 2019). "To confirm that PTBP3 mRNA is overexpressed in prostate cancer cells, we evaluated the PTBP3 expression pattern between prostate cancer and normal tissues samples [on the basis of Gene Expression Omnibus(GEO) and Gene Expression Profiling Interactive Analysis( GEPIA) annotations]." (PMID 30634466, 2019). "H3K27 acetylation detected at analyzed regions of the PTBP3 locus in prostate cancer cells (PC3 and PC3M) may suggest that open chromatin regions are located at positions −63 kb and +48 kb of the PTBP3 promoter, respectively, and may act as epigenetic activation regulators of the PTBP3 gene." (PMID 30634466, 2019). "We performed a 3C experiment using prostate cancer cell lines (PC3 and PC3M) with a statistically significant high expression of PTBP3 versus human skin fibroblasts to identify chromatin interaction across the PTBP3 locus." (PMID 30634466, 2019). "In prostate cancer cell lines PC3 and PC3M, which express high levels of PTBP3 transcripts, 3C analysis demonstrated chromatin interaction between the PTBP3 promoter and distal or proximal fragments encompassing regulatory elements." (PMID 30634466, 2019).
prostate carcinoma (continued). "In both prostate cancer cell lines, PC3M and PC3, ChIP assays targeting H3K27ac revealed that this type of histone modification was located at the same positions as those identified by the 3C assay of long-range chromatin interactions with the PTBP3 promoter." (PMID 30634466, 2019).
breast tumor (2 papers, 2021 to 2023). "Recent studies have defined PTBP3 as a regulator of EMT that acts by governing expression of ZEB1, which establish an oncogenic function of PTBP3 in breast tumor cells." (PMID 37633911, 2023). "For example, PTBP3 can regulate the expression of the transcription factor ZEB1 by binding to the 3'UTR of its mRNA, thereby preventing its degradation, inducing the epithelial-mesenchymal transition of breast tumor cells and promoting their invasive growth and metastasis." (PMID 34234866, 2021).
hyper-IgM syndrome type 2 (2 papers, 2018 to 2024). A hyper-IgM syndrome characterized by the absence of immunoglobulin class switch recombination, the lack of immunoglobulin somatic hypermutations, and lymph node hyperplasia caused by the presence of giant germinal centers. "PTBP3 is a cofactor of activation-induced cytidine deaminase (AID) in B cells, PTBP3 can regulate the recognition of AID to the target sites and further affect hyper-IgM syndrome type 2 caused by AID mutation." (PMID 38405614, 2024).
leukemia (2 papers, 2012 to 2020). A malignant (clonal) hematologic disorder, involving hematopoietic stem cells and characterized by the presence of primitive or atypical myeloid or lymphoid cells in the bone marrow and the blood. "Overexpression of PTBP3, a factor involved in alternative splicing, may inhibit the differentiation of leukemia cells." (PMID 32974175, 2020).
liver cancer (2 papers, 2023 to 2025). An epithelial or non-epithelial malignant neoplasm that arises from the liver. "The 3’ UTR of PTBP3 combined with miR-297 in liver cancer should be mutated to confirm that the inhibitory effect is mediated by PTBP3." (PMID 37633911, 2023). "In this study, PTBP3 was identified as a direct target gene of miR-297 in liver cancer through dual-luciferase reporter gene experiments and the effect of PTBP3 knockdown on HepG2 cells was investigated by cell function assays." (PMID 37633911, 2023). "PTBP3 was identified as a direct target gene of miR-297 in liver cancer and mediated the function of miR-297 in liver cancer cells." (PMID 37633911, 2023). "For example, in liver cancer cell lines, PTBP3 has been identified as a direct target of miR‐297." (PMID 40270362, 2025). "PTBP3 was identified as a direct target gene of miR-297 in liver cancer cells." (PMID 37633911, 2023). "miR-297 and PTBP3 might act as potential therapeutic targets for liver cancer." (PMID 37633911, 2023).
Cholecystitis (1 paper, 2024). The presence of inflammatory changes in the gallbladder. "Next, we analyzed PTBP3 protein expression levels in tissue microarrays containing 50 gallbladder cancer and 50 cholecystitis tissue samples using IHC." (PMID 39116343, 2024). "PTBP3 protein expression was higher in gallbladder cancer tissues than in cholecystitis tissues." (PMID 39116343, 2024).
chronic myelogenous leukaemia (1 paper, 2022). "We found that PTBP3 expression in BeWo cells (human placental choriocarcinoma cells) was the highest in the Human Protein Atlas (HPA) datasets, followed by K-562 (chronic myelogenous leukaemia cells) and OE19 (human oesophageal cancer cells)." (PMID 35359851, 2022).